SLCO1C1 (solute carrier organic anion transporter family member 1C1)
Description:
Mediates the Na(+)-independent high affinity transport of organic anions such as the thyroid hormones L-thyroxine (T4), L-thyroxine sulfate (T4S), and 3,3',5'-triiodo-L-thyronine (reverse T3, rT3) at the plasma membrane. Regulates T4 levels in different brain regions by transporting T4, and also by serving as an export pump for T4S, which is a source of T4 after hydrolysis by local sulfatases. Increases the access of these substrates to the intracellular sites where they are metabolized by the deiodinases. Other potential substrates, such as triiodothyronine (T3), 17-beta-glucuronosyl estradiol (17beta-estradiol 17-O-(beta-D-glucuronate)), estrone-3-sulfate (E1S) and sulfobromophthalein (BSP) are transported with much lower efficiency. Transports T4 and E1S in a pH-insensitive manner. Facilitates the transport of thyroid hormones across the blood-brain barrier and into glia and neuronal cells in the brain.
Synonyms: OATP1C1; OATP-F; OATP-RP5; OATP14; OATPF; SLC21A14; OATP1; OATPRP5
Tractability: Antibody: UniProt places it where antibodies can reach, with high confidence; its Gene Ontology location is reachable by antibodies, with high confidence; UniProt predicts a signal peptide or a membrane-spanning region. PROTAC: ubiquitination databases record sites on it; its protein half-life has been measured.
Target class: Electrochemical transporter; SLC superfamily of solute carriers; SLC21/SLCO family of organic anion transporting polypeptides; Transporter
Gene: Protein-coding gene on chromosome 12 (20,695,332 to 20,753,386, forward strand). Ensembl gene ENSG00000139155.
Subcellular location: Cell membrane
Pathways (Reactome):
Transport of small molecules: Organic anion transport by SLCO transporters
Gene Ontology:
Molecular function: protein binding; thyroid hormone transmembrane transporter activity; transmembrane transporter activity; bile acid transmembrane transporter activity; secondary active transmembrane transporter activity
Biological process: positive regulation of thyroid hormone generation; thyroid hormone transport; transmembrane transport; bile acid and bile salt transport; sodium-independent organic anion transport; transport across blood-brain barrier
Cellular component: basolateral plasma membrane; plasma membrane; membrane
Genetic constraint (gnomAD): Loss-of-function variants: 67 observed, 71.33 expected, observed/expected ratio (o/e) 0.94, 90% interval 0.77 to 1.15. The upper end of that interval is the gene's LOEUF score, 1.15, which puts it in group 5 of 6, group 1 being the genes least tolerant of losing a copy. Missense variants: 871 observed, 799.15 expected, observed/expected ratio (o/e) 1.09, 90% interval 1.03 to 1.15. Synonymous variants: 293 observed, 278.79 expected, observed/expected ratio (o/e) 1.05, 90% interval 0.95 to 1.16.
Homologues: Orthologues: macaque SLCO1C1 (98% identical), chimpanzee SLCO1C1 (92% identical), dog SLCO1C1 (90% identical), guinea pig SLCO1C1 (90% identical), rabbit SLCO1C1 (89% identical), pig SLCO1C1 (88% identical), rat Slco1c1 (85% identical), mouse Slco1c1 (84% identical), tropical clawed frog SLCO1C1 (60% identical), zebrafish slco1c1 (55% identical), Drosophila melanogaster Oatp30B (29% identical). Paralogues in human: SLCO1B3 (44% identical), SLCO1B1 (43% identical), SLCO1A2 (41% identical), SLCO3A1 (31% identical), SLCO2A1 (29% identical), SLCO2B1 (28% identical), SLCO5A1 (27% identical), SLCO4C1 (27% identical), SLCO4A1 (26% identical), SLCO6A1 (21% identical).
Diseases named in the same sentence as SLCO1C1 in open-access papers:
SLCO1C1 is named in the same sentence as 21 diseases in open-access papers, as found by Europe PMC text mining. Sharing a sentence is not in itself a finding about the gene and the disease. The quoted sentences say what the papers report.
Allan-Herndon-Dudley syndrome (3 papers, 2021 to 2022). A syndrome with neuromuscular involvement characterized by infantile hypotonia, muscular hypoplasia, spastic paraparesis with dystonic/athetoic movements, and severe cognitive deficiency. "Mutations in TH transporters like MCT8 (SLC16A2), and OATP1C1 (SLCO1C1) cause juvenile neurodegeneration and brain developmental disease, Allan-Herndon-Dudley syndrome. oatp1c1 (slco1c1) knockout zebrafish also showed a similar phenotype." (PMID 33685490, 2021).
depressive disorder (3 papers, 2023 to 2025). A melancholy feeling of sadness and despair. "In addition, the DiO1, DiO2 Thr92Ala, and SLCO1C1 mutation SNPs show a high sensitivity and specificity in differentiating depressive disorder from BSD." (PMID 37511721, 2023). "Recent findings further highlight that SNPs in DIO1, DIO2 and SLCO1C1 showed high sensitivity and specificity in differentiating depressive disorder from BD, emphasising the role of genetic variations in TH pathways in delineating between different mood disorders." (PMID 40586856, 2025).
Obesity (1 paper, 2021). Accumulation of substantial excess body fat. "Nonetheless, in light of recent results using the Tie2-Cre; Lrp2flx/flx mice, our preliminary data using Slco1c1-CreERT2; Lrp2flx/flx mice indicate that LRP2 at the BBB is not specifically involved in the development of obesity." (PMID 34066779, 2021).
psoriasis (1 paper, 2023). An autoimmune condition characterized by red, well-delineated plaques with silvery scales that are usually on the extensor surfaces and scalp. "In psoriasis, a study evaluated the influence of the SLCO1C1 rs3794271 and PDE3A rs11045392 polymorphisms on anti-TNF response in 130 white patients (from Spain) and showed that patients carrying the C allele obtained a better response (ΔPASI after 3 months) (p = 0.00057)." (PMID 37240048, 2023).
psychomotor developmental delay (1 paper, 2023). "Mutations in the MCT8 gene (SLC16A2) and in the OATP1C1 gene (SLCO1C1) can cause a psychomotor developmental delay in humans." (PMID 37298594, 2023).
serous ovarian cancer (1 paper, 2018). "In serous ovarian cancer, SLCO1B1, SLCO1C1, and SLCO6A1 were observed in a low number of samples only." (PMID 30131693, 2018).
cancer (3 papers, 2021 to 2024). A tumor composed of atypical neoplastic, often pleomorphic cells that invade other tissues. "Six additional genes (SLC10A6, SLC22A1, SLC51A, SLC51B, SLCO1C1, SLCO4C1) were included to finally examine the expression of 15 genes encoding E1-S transporters in the total of 36 pairs of cancer and adjacent control tissue." (PMID 33917029, 2021). "Although other members of the OATP family are expressed in some types of tumors and can transport antitumor drugs, such as OATP1C1 (SLCO1C1), which transports docetaxel, OATP4C1 (SLCO4C1), methotrexate, and OATP5A1 (SLCO5A1), satraplatin, their role in cancer chemoresistance is poorly understood." (PMID 39143954, 2024).
tumor (2 papers, 2018 to 2022). "Excluded from the calculation were SLCO1B1 and SLCO1C1, which were rarely expressed in HGSOC tumor tissues and were never observed in benign cysts (data not shown)." (PMID 30131693, 2018).
SLCO1C1 also shares sentences with these, for which no sentence is quoted: Anxiety (4 papers); hyperthyroidism (3); hypothyroidism (3); depression (2); Central hypothyroidism (1); endotoxemia (1); Macrocephaly (1); mood disorder (1); movement disorder (1); neutropenia (1); ovarian carcinoma (1); psoriatic arthritis (1); Stroke (1).